FOLH1 (folate hydrolase 1)
Diseases named in the same sentence as FOLH1 in open-access papers (continued):
Sharing a sentence is not in itself a finding about the gene and the disease.
tumor (continued). "CIBERSORT-based deconvolution linked FOLH1 to heightened CD8+-T-cell infiltration and showed all three hubs inversely associated with CD4+-T cells, implicating them in shaping the tumor immune milieu." (PMID 40806607, 2025). "There was a strong correlation between endothelial cell abundance (Spearman 0.76) in the tumor microenvironment and FOLH1 expression, with weaker correlations for immune cell types (Spearman 0.04–0.50)." (PMID 38791934, 2024). "Tumor endothelial cells upregulated angiogenesis-associated genes including CHST1, FOLH1, and MMP1522–24." (PMID 38744958, 2024). "The monoclonal mouse anti-human PSMA/FOLH1/NAALADase I antibody was used for staining the primary tumor." (PMID 36476583, 2022). "ST analysis confirmed CD8+ cell infiltration in MPC prostate with 9.1–95.5% of CD8A+ positive spots overlapping with FOLH1+ spots, indicating the proximity of effector T-cells and PSMA-expressing cancer cells in the tumour tissue." (PMID 36243890, 2022). "LvCaP-1 expressed NKX3-1, HOXB13 (mutated G84E), FOLH1, KLK2, and KLK3, but with only a low level of PSA secretion (i.e., serum PSA of 1.4 ± 0.4 ng/mL/g tumor)." (PMID 33724955, 2021). "One FOLH1+ paraffin section contained both p‐ and mMCC tumours (from the same patient), suggesting that biopsy of pMCC can predict some degree of FOLH1+ homogeneity in a meta‐stasis." (PMID 34541577, 2021). "FOLH1 mRNA expression was higher in benign liver tissue (measured in normalized reads: mean 1034, range 206-1932) than in tumor (mean 432, range 4-3585) tissue (t-test p<0.0001)." (PMID 31289613, 2019). "The only statistically significant correlation for FOLH1 mRNA expression in tumor tissue was with histological grade of the tumor (Pearson’ s r = -0.13, p = 0.011)." (PMID 31289613, 2019). "To validate this finding we performed IHC analysis for PSMA on a number of tumours with either low or high FOLH1 FPM values." (PMID 31747973, 2019). "Only 10.3% of the tumor samples demonstrated FOLH1 mRNA expression more than average of that in normal tissue." (PMID 31289613, 2019). "We believe that the PCA3 is more specific for tumor detection than the FOLH1 marker, which presents a high variation on gene expression among PCa and BPH patients and its utilization as a biomarker is highly controversial (unpublished data)." (PMID 18823560, 2008). "KLK3 and FOLH1 are expressed in tumours even in early disease and may be representative of disease burden." (PMID 39840448, 2025). "We aimed to determine whether comparisons of FOLH1 expression derived from large-scale transcriptomic profiling of tumor cohorts and of related normal tissue could determine tumor types for which PSMA-targeting theranostics may have utility." (PMID 40227800, 2025). "We, therefore, aimed to evaluate whether histology-specific expression of FOLH1 may show patterns suggestive of tumor specificity for tumor types known to respond well to PSMA radioligand interventions or show significant uptake on diagnostic PSMA PET imaging." (PMID 40227800, 2025). "Expression of the FOLH1 gene, which encodes PSMA, is dynamically regulated by androgen receptor (AR) signaling—it is upregulated by androgen deprivation but downregulated after prolonged AR pathway inhibition or in AR-independent tumor evolution." (PMID 41374949, 2025). "Comprehensive RNA analysis highlights the correlation of FOLH1 expression with an angiogenic gene signature and increased endothelial cell abundance in the tumor microenvironment, suggesting potential therapeutic implications for tumors with high FOLH1 expression." (PMID 38791934, 2024). "While in our study, microdissection was performed prior to sequencing to facilitate the enrichment of tumor elements, we were not able to distinguish between the tumor cells and tumor-associated neovasculature FOLH1 expression." (PMID 38791934, 2024). "Our analysis did not demonstrate any significant association of FOLH1 with immune signatures, tumor-infiltrating immune cells, or PD-L1." (PMID 38791934, 2024).
tumor (continued). "We correlated components of the tumor microenvironment with FOLH1 expression." (PMID 38791934, 2024). "A total of 81 MCC tumours were evaluated for FOLH1 expression by standard immunohistochemistry." (PMID 34541577, 2021). "The majority of FOLH1+ vessels were identified in the periphery of infiltrating tumour cells." (PMID 34541577, 2021). "67% (54/81) of all cases, 77% (24/31) pMCC and 60% (30/50) mMCC tumours were FOLH1+." (PMID 34541577, 2021). "Additionally, FOLH1/PSMA inhibition resulted in tumour growth regression and size decrease in animal models." (PMID 33312730, 2020). "We also analysed the association of PSMA (FOLH1) expression with patient survival using the TCGA GBM data set (n = 567 mRNA microarray samples), which contains transcriptome data of the whole tumour bulk comprising mostly of tumour cells." (PMID 32390293, 2020). "IHC revealed expression of PSMA on the blood vessels of tumours with high FOLH1 FPM values." (PMID 31747973, 2019). "We further hypothesized that the expression of FOLH1 in tumor relative to normal tissue may differentiate between tumor histologies that have historically responded to PSMA radioligand therapies or demonstrated significant uptake on diagnostic PSMA PET imaging versus those that did not." (PMID 40227800, 2025). "Clinical data on FOLH1‐ targeting with α‐emitters (i.e., two protons and two neutrons) in prostate cancer (PCa) is promising and suggests that α‐emitters could be considered for hypoxic tumours." (PMID 34541577, 2021). "By modifying the epidermal growth factor receptor and folate hydrolase 1 (PSMA) of bi-specific antibodies on the LNP surface, they were able to achieve mRNA expression in tumor tissues with an ∼8-fold increase compared to untargeted modifications in vivo." (PMID 41210587, 2025). "Erythroblastosis virus E26 (ETS)-fusion-positive tumours, such as transmembrane-protease and serine-2-ETS-related gene (TMPRSS2-ERG), demonstrate stronger FOLH1 promote activity." (PMID 41301079, 2025). "For example, cancer RNA biomarkers such as KRAS, PCA3, PIK3CA mutants, EGFRvIII, FOLH1, KLK2, KLK3, EML4-ALK, and NYP have been reported to be sequestered by platelets that actively uptake tumor-derived material." (PMID 39274207, 2024). "Studies have reported that inhibition of FOLH1/PSMA ameliorates IBD symptom in mice models and also leads to tumor regression in preclinical models." (PMID 35144655, 2022). "In order to determine the effectiveness of the grouping strategy between the low- and high-expression groups of CYB561 and FOLH1, the ESTIMATE method was applied to evaluate Tumor Purity, ESTIMATE Score, Immune Score, and Stromal Score." (PMID 35836577, 2022). "Next, we divided the tumor patients into high- and low-expression groups according to the optimal cut-offs in CYB561 and FOLH1 (4.67 in CYB561, 2.64 in FOLH1) for clinical prognostic analysis." (PMID 35836577, 2022). "Further, tumor-derived platelets biomarkers, as KLK3, FOLH1, and NPY, enable prediction after abiraterone therapy in castration resistant prostate cancer (CRPC) and KLK2, KLK3, and FOLH1 were associated with short OS." (PMID 33673461, 2021). "In the DNET, considered as a benign grade I tumour, we found high expression levels of ErbB3, FGFR2, FOLH1 and AXL." (PMID 31747973, 2019). "Emerging biomarkers include cell-free DNA epigenomic signals at the FOLH1 (PSMA) locus: acting as a surrogate for tumour PSMA expression, correlated highly with total-tumour PSMA-PET/CT SUVmean (p < 0.05), and was potentially a predictive biomarker of therapeutic response." (PMID 41543663, 2026). "To date, a comprehensive assessment of FOLH1 expression across sites of metastasis is lacking, and PSMA IHC expression studies have largely been limited to the assessment of nephrectomy tumor specimens." (PMID 38791934, 2024). "However, CNS tumors exhibited lower FOLH1 expression relative to normal brain tissue, indicating a lack of tumor specificity." (PMID 40227800, 2025).
tumor (continued). "Upon AR pathway inhibition, there may be a consequent up-regulation of PSMA; however, if the tumor undergoes neuroendocrine differentiation (NED), driven by factors like N-Myc and EZH2, epigenetic silencing of FOLH1 results in PSMA-low or -negative subclones." (PMID 40806607, 2025).
cancer (746 papers, 2008 to 2026). A tumor composed of atypical neoplastic, often pleomorphic cells that invade other tissues. "The KLK3 and FOLH1 proteins were targets for diagnostic and therapeutic agents; the remaining genes were targets for treatment or palliative agents, mostly in approved or investigational status in various types of cancer." (PMID 39595075, 2024). "FOLH-1 enzymes and other important molecular activities lead to increased angiogenesis and cell proliferation in tissues and cancers, which further increase expression of PSMA in advanced stages of the disease." (PMID 38760621, 2024). "FOLH1 was reported to be upregulated in PCa, and its expression has been correlated with cancer aggressiveness." (PMID 34437475, 2021). "Other genes involved in one-carbon metabolism were found transcriptionally repressed in HCC tissue, although the methylation pattern was unchanged in BHMT1, BHMT2, CBS, GNMT, and MTHFD2L in cancer as compared to cancer-free tissue or decreased in FOLH1." (PMID 25945129, 2015). "We selected those genes with functions known to be associated with cancer of which there were 12—SNVs: NOTCH2, PIK3CG, IL2RB, BAI3, FREM2 and RERE; indels: UTRN, CDHR3, NCOA5, CABYR, HOTAIR and FOLH1." (PMID 26017033, 2015). "Interestingly, PCa cells can alter the transcriptome of infiltrating CD8+ effector T cells to express tumor marker genes such as FOLH1, mediated by cancer cell-derived extracellular vesicles (EVs)." (PMID 40427733, 2025). "This study systematically analyzed large-scale gene expression datasets to assess whether FOLH1, the gene encoding PSMA, is differentially expressed in various cancers compared to normal tissues." (PMID 40227800, 2025). "This gap in research into FOLH1/PSMA expression is even more pronounced in murine cancer models." (PMID 38760621, 2024). "Further investigation into FOLH1 and PSMA expression in human cancers is crucial for understanding expression patterns and the connection between FOLH1 gene expression and PSMA protein levels." (PMID 38760621, 2024). "Among these, open reading frames of at least 23 genes (23/42 = 55%), including cancer genes such as ERBB2, FOLH1 and ULK2, were predicted to be altered by these SMNTs and their combined structural variant events in the vicinity." (PMID 32024997, 2020). "PSMA (prostate-specific membrane antigen; synonym: folate hydrolase 1 (FOLH1)) is a cell-surface antigen with abundant and virtually universal expression in PCa which increases as the cancer progresses." (PMID 24517338, 2014). "PCa related exosomes from clinical samples in general show the presence of some cancer related proteins such as CD9, CD81, and TSG101, Annexin A2, Fatty Acid Synthase (FASN) and a PCa specific biomarker, FOLH1 (Prostate Specific Membrane Antigen or PSMA)." (PMID 24351670, 2013). "We found also several genes underexpressed in subset of cancer samples like KLK3, FOLH1, SPON2, A2M, and PCP4." (PMID 22811706, 2012). "Cancer cell lines originating from same organ often gathered in the same cluster, such as C2 [COAD/READ-STAD-PAAD], a group of digestive system cancers whose common features were the high expression of CNKSR1, FOLH1, ADGRG1, SMAD7, LRATD1 and MVP." (PMID 32874774, 2020).
prostate (50 papers, 2004 to 2025). "FOLH1(PSMA) a male reproductive organ cancer associated gene was up-regulated in young patients with well differentiated tumors, potential target of toxin-based immunotherapy." (PMID 33575208, 2020).
adenocarcinoma (36 papers, 2013 to 2025). A common cancer characterized by the presence of malignant glandular cells. "Even within the adenocarcinoma specimens, FOLH1 expression displayed a significant, although modest, inverse correlation with the NEPC gene signature." (PMID 41056440, 2025). "FOLH1 expression was significantly lower in the neuroendocrine (2.92 log2[TPM + 1] (q < 0.0001) and mixed adenocarcinoma/neuroendocrine specimens (7.49 log2[TPM + 1]) (q = 0.008) compared to adenocarcinoma (8.64 log2[TPM + 1])." (PMID 41056440, 2025).
CNS tumors (6 papers, 2020 to 2025). "In this study, we performed a comprehensive bioinformatics analysis of publicly available databases to get a better understanding of FOLH1/PSMA expression in adult and pediatric CNS and non-CNS tumors in comparison to normal tissues." (PMID 40227800, 2025).
FOLH1 also shares sentences with these, for which no sentence is quoted: neuroendocrine tumors (106 papers); xerostomia (89); thyroid cancer (60); renal cell carcinoma (55); bone metastasis (51); hepatocellular carcinoma (42); lung carcinoma (41); pancreatic cancer (23); benign prostatic hyperplasia (20); benign tumors (20); triple-negative breast carcinoma (19); anemia (18); meningioma (18); adenoid cystic carcinoma (17); bladder cancer (17); Thrombocytopenia (17); metastatic carcinoma (16); non-small cell lung carcinoma (16); infection (15); colon carcinoma (13); differentiated thyroid carcinoma (13); salivary gland cancer (13); metastasis (11); gastric cancer (10); hemangioma (10); neurological disorders (10); thyroid nodule (10); kidney cancer (9); medullary thyroid carcinoma (9); urothelial carcinoma (9).
A further 306 diseases each share a sentence with FOLH1 in 8 papers or fewer.